Y_RNA (Y RNA )
Gene: Miscellaneous RNA gene on chromosome 6 (89,841,329 to 89,841,424, forward strand). Ensembl gene ENSG00000199630.
Homologues: Orthologues: chimpanzee Y_RNA (100% identical), dog Y_RNA (71% identical). Paralogues in human: Y_RNA (76% identical), Y_RNA (74% identical), Y_RNA (72% identical), Y_RNA (71% identical), Y_RNA (70% identical), Y_RNA (69% identical), RNY1 (68% identical), Y_RNA (68% identical), RNY1P5 (67% identical), Y_RNA (67% identical), RNY1P7 (66% identical), Y_RNA (66% identical), and 85 more.